TNK2 (tyrosine kinase non receptor 2)
Diseases named in the same sentence as TNK2 in open-access papers (continued):
Sharing a sentence is not in itself a finding about the gene and the disease.
colon carcinoma (4 papers, 2021 to 2023). "Hence, these results revealed that the extent of TNK2 promoter demethylation might cause the high TNK2 expression in colon cancer." (PMID 34421982, 2021). "In our study, we verified that the expression of TNK2 is upregulated in colon cancer cells compared with normal colon cells, and it was found to directly bind to miR-125a-3p, which was downregulated in such cell lines." (PMID 34421982, 2021). "A box plot illustrates that TNK2 expression was remarkably higher in colon cancer tissues than in adjacent normal tissues, and TNK2 was overexpressed at different stages of tumor progression." (PMID 34421982, 2021). "In our study, the UALCAN and ONCOMINE datasets revealed that the expression of TNK2 is higher in colon cancer tissues than that in normal tissues." (PMID 34421982, 2021). "In the present study, we used microarray and RNA sequencing data obtained from a public dataset to investigate TNK2 expression in colon cancer." (PMID 34421982, 2021). "Using analysis of DNA methylation data from UALCAN, we verified that the TNK2 promoter methylation level was reduced in colon cancer compared with that in normal tissues, which was the opposite of TNK2 expression." (PMID 34421982, 2021). "Although the expression levels of TNK2 were validated in colon cancer tissues, additional experiments are required in the future to confirm the expression and function of TNK2 in colon cancer." (PMID 34421982, 2021). "RT-qPCR and western blotting were performed to investigate the expression of TNK2 in colon cancer cells." (PMID 34421982, 2021). "The use of both datasets achieved a unified result; Kaplan-Meier survival analysis revealed that colon cancer patients with lower TNK2 expression had better prognoses than those with higher TNK2 expression." (PMID 34421982, 2021). "Materials and methods: The expression of TNK2 and miR-125a-3p in colon cancer tissues was analyzed using data deposited on public databases including UALCAN and ONCOMINE." (PMID 34421982, 2021). "We further evaluated the expression of TNK2 in colon cancer and paired normal tissues at different tumor stages." (PMID 34421982, 2021). "In this study, we found that the expression of TNK2 was upregulated in colon cancer cell lines and that it directly binds to miR-125a-3p, which is downregulated in colon cancer cells." (PMID 34421982, 2021). "In the present report, UALCAN datasets were employed to identify TNK2 promoter methylation levels in colon cancer cells." (PMID 34421982, 2021). "We then performed RT-qPCR and WB to verify that the expression of TNK2 in colon cancer cell lines was higher than that in normal colon cells." (PMID 34421982, 2021). "According to immunohistochemical data from the HPA database, staining revealed that TNK2 exhibited low expression in endothelial cells in normal colon tissue samples and high expression in malignant cells in colon cancer tissues." (PMID 34421982, 2021). "GEPIA and LinkedOmics datasets indicated that colon cancer patients with lower TNK2 expression had better prognoses than those with higher TNK2 expression." (PMID 34421982, 2021). "Immunohistochemical staining revealed TNK2 expression in colon cancer tissues was more pronounced than that in normal colon tissues." (PMID 34421982, 2021). "By regulating the expression of TNK2 and miR-125a-3p in colon cancer cells, their functions and potential mechanisms were explored." (PMID 34421982, 2021). "TNK2 and miR-125a-3p could also serve as biomarkers and potential prognostic markers in colon cancer." (PMID 34421982, 2021). "We found that the elevated expression of TNK2 may be related to promoter methylation levels in colon cancer." (PMID 34421982, 2021). "We presumed that high expression of TNK2 might be related to increased demethylation levels in colon cancer, in order to verify this assumption, we will design and perform some more experiments in the next study." (PMID 34421982, 2021).
colon carcinoma (continued). "The function of CYTH1 in colon cancer is poorly understood, we hypothesized that TNK2 is possible to work in synergy with CYTH1 or other co-expressed proteins." (PMID 34421982, 2021). "Our results indicated that the expression of TNK2 and miR-125a-3p affects proliferation and invasion by colon cancer cells, and the high expression of TNK2 in colon cancer might play a vital role in tumor prognosis." (PMID 34421982, 2021). "In stages 2, 3, and 4 of colon cancer, TNK2 promoter methylation levels were also reduced." (PMID 34421982, 2021). "CCLE and EMBL-EBI databases also verified that TNK2 is highly expressed in colon cancer cell lines." (PMID 34421982, 2021). "Furthermore, bioinformatic analysis was used to evaluate the function of TNK2 in colon cancer, including co-expression of genes and promoter methylation levels." (PMID 34421982, 2021). "Kaplan–Meier survival analysis was considered as a prognostic index of TNK2 in colon cancer." (PMID 34421982, 2021). "We also identified genes co-expressed with TNK2 in colon cancer." (PMID 34421982, 2021). "Additionally, colon cancer patients with lower TNK2 expression had better prognoses than those with higher TNK2 expression." (PMID 34421982, 2021). "Taken together, we systemically demonstrated that TNK2 expression was increased in colon cancer and that such expression may be regulated by miR-125a-3p or TNK2 promoter demethylation levels." (PMID 34421982, 2021). "This study is the first to explore the relationships between TNK2 and miR-125a-3p, and their potential mechanisms involved in colon cancer, which may benefit the diagnosis and treatment of colon cancer patients." (PMID 34421982, 2021). "Hence, the high expression of TNK2 was a prognostic factor for colon cancer." (PMID 34421982, 2021). "Moreover, EMBL-EBI data were also used to verify the expression of TNK2 translational factors in different colon cancer cell lines, and the results indicated that TNK2 levels were increased in most colon cancer cell lines when compared with the normal colon cell line." (PMID 34421982, 2021). "Although a growing number of studies have reported TNK2 expression and its molecular mechanisms involved in different cancers, there is still not much to be understood of colon cancer in this context." (PMID 34421982, 2021). "We investigated the prognostic value of TNK2 using GEPIA and LinkedOmics databases in colon cancer." (PMID 34421982, 2021). "The expression of TNK2 was affected by the binding of miR-125a-3p to the 3′-UTR of TNK2, and both were involved in regulating a pathway critical for the proliferation and invasion of colon cancer cells." (PMID 34421982, 2021).
glioma (4 papers, 2022 to 2024). A benign or malignant brain and spinal cord tumor that arises from glial cells (astrocytes, oligodendrocytes, ependymal cells). "One of these proteins, the non‐receptor kinase activated CDC42 kinase 1 (TNK2) has a documented role in neurite migration, and phosphorylation of this Tyr plays a role in glioma oncogenesis." (PMID 38989636, 2024). "In addition, TNK2 could stimulate PDGFR-β activity and AKT activation to promote tumor cell cycle progression, proliferation, and tumorigenesis and played a pivotal role in PDGFR-induced AKT signaling in glioma tumorigenesis." (PMID 36419652, 2022).
Ewing sarcoma (3 papers, 2010 to 2016). A small round cell tumor that lacks morphologic, immunohistochemical, and electron microscopic evidence of neuroectodermal differentiation. "This is contrary to our observation in Ewing's sarcoma cells, wherein we showed that TNK2 knockdown is indeed responsible for causing cell death through apoptosis." (PMID 20718987, 2010). "TNK2 gains have been found in breast, prostate, lung, pancreas, brain, Ewing’s sarcoma and the pharmaceutical agent dasatinib is a known inhibitor." (PMID 26901676, 2016). "In summary, RNAi-based phenotypic profiling proved to be a powerful gene target discovery strategy, leading to successful identification and validation of STK10 and TNK2 as two novel potential therapeutic targets for Ewing's sarcoma." (PMID 20718987, 2010). "We showed that two kinases, STK10 and TNK2, are important in survival of Ewing's sarcoma cells and represent potential therapeutic targets for future drug development in this disease." (PMID 20718987, 2010). "Secondary validation and preliminary mechanistic studies highlighted the kinases STK10 and TNK2 as having important roles in growth and survival of Ewing's sarcoma cells." (PMID 20718987, 2010). "The first module includes STK10, TNK2 and TAOK3, which were identified to be significant across all four Ewing's sarcoma cell lines." (PMID 22761558, 2012). "We confirmed the effects of silencing of STK10, TNK2, and PLK1 on growth and survival of Ewing's sarcoma cells by repeating the cell based assay in 384-well plates using a different lot of siRNA having the same sequences as the kinase library siRNA." (PMID 20718987, 2010). "Silencing of STK10, TNK2 and PLK1 by both siRNA sequences inhibited cell growth in the four Ewing's sarcoma cell lines as measured by cell number." (PMID 20718987, 2010). "In this study, we chose three genes STK10, TNK2 and PLK1 for further validation studies as these genes were prioritized by having significant Z-score values for both siRNAs across all screens in the four Ewing's sarcoma cell lines." (PMID 20718987, 2010). "Mining of gene-expression data indicate that both STK10 and TNK2 are not highly over-expressed in Ewing's sarcoma, hence over-expression of these genes may not be a driver for their functional specificity in this disease." (PMID 20718987, 2010). "On browsing their target gene lists we did not see STK10 and TNK2 as "hits" in any of their screens, which also points to the fact that these two targets might be specific to Ewing's sarcoma." (PMID 20718987, 2010).
juvenile myelomonocytic leukemia (3 papers, 2023 to 2024). A myelodysplastic/myeloproliferative neoplasm of childhood that is characterized by proliferation principally of the granulocytic and monocytic lineages. "Pharmacological suppression of TNK2 prevented the activation of MAPK/ERK signaling in juvenile myelomonocytic leukemia (JMML) and reduced the size of the tumor." (PMID 38650011, 2024).
leukemia (3 papers, 2020 to 2025). A malignant (clonal) hematologic disorder, involving hematopoietic stem cells and characterized by the presence of primitive or atypical myeloid or lymphoid cells in the bone marrow and the blood. "TNK2 has been implicated as a proto-oncogene in several cancers, including leukemia, prostate, and breast." (PMID 34504101, 2021).
osteosarcoma (3 papers, 2018 to 2024). A usually aggressive malignant bone-forming mesenchymal neoplasm, predominantly affecting adolescents and young adults. "ZNF692 enhances the proliferation, migration, and invasion of osteosarcoma cells via TNK2-dependent stimulation of the MEK/ERK signaling pathway." (PMID 38650011, 2024). "In order to investigate the function of TNK2 in osteosarcoma, we developed a targeted siRNA to inhibit TNK2 and created a plasmid to overexpress TNK2." (PMID 38650011, 2024). "The use of luciferase reporter assay and ChIP assay provides confirmation that ZNF692 increases the transcription of TNK2 in osteosarcoma cells through binding to the promotor region." (PMID 38650011, 2024). "Collectively, our findings indicate that ZNF692 enhances the proliferation, migration, and invasion of osteosarcoma cells by activating the MEK/ERK pathway via TNK2." (PMID 38650011, 2024). "We created a composite panel by integrating ZNF692 and TNK2 to forecast the prognosis of osteosarcoma." (PMID 38650011, 2024). "ZNF692 promotes proliferation, migration and invasion of osteosarcoma cells through TNK2-mediated MEK/ERK pathway activation." (PMID 39717098, 2024). "ZNF692 promotes the proliferation, migration, and invasion of osteosarcoma cells via the TNK2-dependent stimulation of the MEK/ERK signaling pathway." (PMID 38650011, 2024). "We next examined the impact of TNK2 knockdown or overexpression on the malignant properties of osteosarcoma cells." (PMID 38650011, 2024). "In the same way, the inhibition of TNK2 in osteosarcoma cells partly counteracted the enhancing impact of ZNF692 overexpression on P-MEK1/2 and P-ERK1/2." (PMID 38650011, 2024). "In addition, ZNF692 specifically interacts with the promoter region of TNK2 and stimulates the transcription of TNK2 in osteosarcoma cells." (PMID 38650011, 2024). "Here, we have provided data that supports the oncogenic role of TNK2 in osteosarcoma." (PMID 38650011, 2024). "In addition, the Kaplan-Meier survival analysis conducted on the TCGA osteosarcoma cohort indicated that elevated TNK2 expression was linked to a negative prognosis in patients with osteosarcoma." (PMID 38650011, 2024). "In addition, an increased expression of TNK2 was shown to correlate with a worse overall survival rate in patients, indicating that TNK2 might serve as a promising prognostic biomarker for osteosarcoma." (PMID 38650011, 2024). "In order to investigate the involvement of TNK2 in the activation of the MEK/ERK signaling pathway by ZNF692, we altered the expression of TNK2 in osteosarcoma cells with either reduced or increased levels of ZNF692." (PMID 38650011, 2024). "In order to validate this in osteosarcoma cells, we measured the protein levels of MEK1/2, P-MEK1/2, ERK1/2, and P-ERK1/2 in 143B and U2OS cells that were either depleted or overexpressed with TNK2." (PMID 38650011, 2024).
schwannoma (3 papers, 2011 to 2023). A benign, usually encapsulated slow growing tumor composed of Schwann cells. "Collectively, these data identify brigatinib as a direct and potent inhibitor of multiple kinases, including FAK1 (PTK2) and FAK2 (PTK2B), and novel targets, GAK and TNK2, in both arachnoid and schwannoma cells." (PMID 34264955, 2021).
thyroid cancer (3 papers, 2020 to 2024). "MOF activates the PI3K/AKT pathway by binding to the TNK2 promoter to promote thyroid cancer proliferation and inhibit apoptosis." (PMID 36523971, 2022). "We verified the correlation between TNK2, DYK1B, MAP2K2 and MOF expression in the TCGA database, and found that in thyroid cancer cells, they all had a strong positive correlation with MOF expression." (PMID 33519470, 2020). "In this study, we reported that MOF, which was upregulated in most thyroid cancer, activated the PI3K/AKT pathway through binding TNK2 promoter." (PMID 33519470, 2020). "Compared with thyroid cell lines N-thy, TNK2 and p-AKT was upregulated in thyroid cancer cell lines BHP-10-3 and TT2609." (PMID 33519470, 2020).
triple-negative breast carcinoma (3 papers, 2017 to 2020). An invasive breast carcinoma which is negative for expression of estrogen receptor (ER), progesterone receptor (PR), and human epidermal growth factor receptor 2 (HER2). "We believe this clinical result when added to the results from our in vitro and in vivo studies provides strong evidence to support identifying TNK2 as a novel target for personalized therapy for patients with basal-like/triple negative breast cancers that express high levels of this protein kinase." (PMID 27902967, 2017).
Chronic Myeloid Leukemia (2 papers, 2021 to 2024). "In Chronic Neutrophilic Leukemia (CNL) and atypical Chronic Myeloid Leukemia (CML), many CSF3R oncogenic mutations have been reported to segregate to two distinct regions of CSF3R, leading to preferential downstream signaling pathways through the SRC family–TNK2 or JAK kinases." (PMID 34573308, 2021).
endometrial carcinoma (2 papers, 2014 to 2021). A malignant tumor arising from the epithelium that lines the cavity of the uterine body. "Immunoblotting confirmed that TNK2 and DDR1 are endogenously expressed in endometrial cancer cells." (PMID 25427824, 2014). "However, from an analysis of the TCGA endometrial cancer data, increased TNK2 and DDR1 copy number appears to reflect regional gains rather than focal amplification, thus making their potential biological relevance in endometrial cancer difficult to predict." (PMID 25427824, 2014). "Immunoblotting confirmed TNK2 and DDR1 expression in endometrial cancer cell lines." (PMID 25427824, 2014).
infantile spasms (2 papers, 2024). A rare epilepsy syndrome characterized by onset of epileptic spasms in infants between 2 and 12 months of age, and rarely up to 24 months. "The first case was a girl with infantile spasms and hypsarrhythmia since 13 months of age with compound heterozygosity for TNK2 gene mutations c.2860 G>T or p.Glu954Ter and c.3004 G>T or p.Gy1002Cys." (PMID 39493104, 2024).
liver cancer (2 papers, 2020 to 2023). An epithelial or non-epithelial malignant neoplasm that arises from the liver. "Research shows that chymotrypsin 1, tyrosine kinase non-receptor 2 and transforming growth factor are up-regulated in liver cancer cells through gene hypomethylation β Receptor II promotes tumor angiogenesis." (PMID 38304027, 2023).
endometrial tumors (1 paper, 2014). "Overall, among the 112 tumors in this study, TNK2 was somatically mutated in 2.2% (1 of 45) of serous, 4.8% (1 of 21) of clear cell, 7.3% (3 of 41) of endometrioid, and 20% (1 of 5) of mixed histology endometrial tumors." (PMID 25427824, 2014). "We next used quantitative real-time PCR to determine whether TNK2 or DDR1 were affected by copy number alterations among the 112 endometrial tumors in this study." (PMID 25427824, 2014). "We therefore extended our analysis of TNK2 and DDR1 to sequence the remaining coding exons from the 40 tumors in the discovery screen and to sequence all coding exons of TNK2 and DDR1 from another 72 primary endometrial tumors consisting of 10 clear cell, 21 serous, and 41 endometrioid tumors." (PMID 25427824, 2014).
endometrioid tumor (1 paper, 2014). A benign, borderline, or malignant epithelial tumor of the female reproductive system characterized by the presence of glands and/or cysts lined by neoplastic cells that resemble endometrial cells. "Of the three endometrioid tumors that harbored somatic DDR1 or TNK2 mutations, two cases (T88 and T117) were grade 1 and one case (T131) was grade 3." (PMID 25427824, 2014). "The single endometrioid tumor displaying a copy number gain of TNK2 was a grade 2 tumor." (PMID 25427824, 2014). "Somatic copy number increases of TNK2 were detected in 8.9% (4 of 45) of serous tumors and in 2.4% (1 of 41) of endometrioid tumors, but in none of the clear cell tumors." (PMID 25427824, 2014).
epilepsy (1 paper, 2024). A brain disorder characterized by episodes of abnormally increased neuronal discharge resulting in transient episodes of sensory or motor neurological dysfunction, or psychic dysfunction. "This is the fourth case report of epilepsy with biallelic mutations in the TNK2 gene, to the best of the authors’ knowledge." (PMID 39493104, 2024). "To date, three families with homozygous/compound heterozygous variants in the TNK2 gene and epilepsy have been described in medical literature." (PMID 39493104, 2024). "Our case is the fourth reported case of association of epilepsy with a biallelic mutation in the TNK2 gene." (PMID 39493104, 2024). "We report an infant with clinical features of Williams syndrome and TNK2 gene-related epilepsy who was diagnosed on exome sequencing which simultaneously diagnosed both the microdeletion and TNK2 gene variant in the patient." (PMID 39493104, 2024). "Thus, the recurrence risk of Williams syndrome in the next child of the couple was negligible but the recurrence risk of TNK2 gene-related epilepsy was likely to be 25 % in every pregnancy." (PMID 39493104, 2024). "We describe a rare co-occurrence of Williams syndrome and TNK2 gene-related epilepsy in a child born of consanguineous parents." (PMID 39493104, 2024).